LOXL2 (lysyl oxidase like 2)
Diseases named in the same sentence as LOXL2 in open-access papers (continued):
Sharing a sentence is not in itself a finding about the gene and the disease.
tumor (continued). "To investigate the role of CBPRS in the tumour microenvironment (TME) at the single-cell transcriptome level, we analysed the expression patterns of SOD1, MUC2, FKBP4, LOXL2, GPC1 and SNAI3 in different cell types." (PMID 38577594, 2024). "In the hypoxic environment of tumour cells, increased levels of LOX and LOXL2 result in irregular collagen alignment, leading to matrix restructuring." (PMID 39247609, 2024). "With respect to microscopic features of the primary tumor in an orthotopic model of PANC-1 group, cancer cells expressed LOXL2 and N-WASP, as confirmed via IHC staining for each primary antibody." (PMID 38560567, 2024). "In this study, we analysed the effect of DFOM in ESCC tumour progression by targeting LCN2, and the LCN2/LOXL2/MMP9 complex as well." (PMID 37753805, 2023). "In summary, the TCGA screening analysis suggests that LOXL2 mutational burden is not a major factor that globally affects the fitness of human tumours, although it is possible that specific mutations could be important in particular tumour types." (PMID 37762708, 2023). "The reduction in the amount of LOXL2 interferes with ECM remodelling and influences the immunity of the tumour." (PMID 37762708, 2023). "To summarize, our study shows that DHA significantly inhibits OS cells proliferation, migration, and invasion by suppressing the expression of LOXL2, a tumor-promoting factor, and reducing VEGFA expression by directly regulating LOXL2." (PMID 37056396, 2023). "Additional gene analysis revealed an upregulation of genes related to the tumor invasion, like matrix metalloproteinase 14 (MMP14) or lysyl-oxidase like 2 (LOXL2)." (PMID 37686288, 2023). "Nevertheless, we provide evidence that LCN2/LOXL2, LCN2/MMP9, LOXL2/MMP9, and LLM affect tumour growth and progression in a synergistic manner." (PMID 37753805, 2023). "Another negative regulator of LOXL2 is the tripartite motif-containing protein 44 (TRIM44), a regulator of tumour immunity in gastric cancer." (PMID 37762708, 2023). "Following these observations, additional evidence has accumulated suggesting that lysyl oxidases, such as LOXL2 and LOX, promote desmoplasia under various conditions and, as a result, promote tumor cells invasiveness and tumor metastasis." (PMID 35682926, 2022). ", it has been shown that diffusion of doxorubicin in tumor spheroids is hampered by the overexpression of LOX and LOXL2." (PMID 36114508, 2022). "At present, the tumor-promoting effects of LOX family (especially LOX and LOXL2) have been confirmed by more and more studies." (PMID 36293126, 2022). "It was found that LOXL2, PLOD2, MMP14 and SPOCK1 were upregulated in tumor samples, whereas DCN was downregulated in tumor specimens." (PMID 36186418, 2022). "Lysyl-oxidase like-2 (LOXL2) regulates extracellular matrix remodeling and promotes tumor invasion and metastasis." (PMID 36209516, 2022). "The secretion of LOXL2 and LOXL4 by breast cancer tumor cells results in increased crosslinking of collagen in the lung, one of the main sites of metastasis for this tumor type." (PMID 36497411, 2022). "Several lysyl-oxidase family members, notably LOX, LOXL2 and LOXL3 have been found to be upregulated by hypoxia and to enhance tumor metastasis." (PMID 36232621, 2022). "As for LOXL2, its expression level was found to be higher in HCC tissues compared with non-tumor tissue." (PMID 35311155, 2022). "However, reducing tumour collagen production by deleting Col1a1 in αSMA-expressing cells or upon treatment with anti–lysyl oxidase like-2 antibody accelerated progression of pancreatic cancer, suggesting that a collagen-rich ECM may also have tumour-protecting functions." (PMID 35760868, 2022). "Consistent with LOXL2 promotion of tumor development and progression, LOXL2 knockdown and overexpression in human PDAC cell lines suggest oncogenic roles of LOXL2 in tumor growth and liver metastasis both in vitro and in vivo." (PMID 34836938, 2021).
tumor (continued). "Tumor stages and nodal stages had significant correlation with HIF-1α expression and localization of LOXL-2 immunoexpression respectively." (PMID 33639646, 2021). "Considering the expression level of LOX family in GC tumor tissues and their prognostic values in GC, LOX and LOXL2 were taken into next functional enrichment analysis." (PMID 35126449, 2021). "Next, we calculated the EMT scores for these cell lines and tumor samples using three different EMT scoring methods (76GS, KS, MLR) and checked their correlation with LOXL2." (PMID 33807227, 2021). "It was also shown that tumor cells alone can modulate the gene expression profile of naïve MSCs, including IL-6, BST2, ADAMTS12, MX2, LOXL2 and GREM1." (PMID 34513701, 2021). "OSM increases the tumor cell invasive capability by inducing an EMT response and, as we have just shown for the first time, upregulating LOXL2 expression." (PMID 34011405, 2021). "It is possible that during tumor progression, some cancer cells undergo the EMT program and start to express LOXL2." (PMID 31462706, 2020). "Lysyl oxidase-like 2 (LOXL2) is a member of the lysyl oxidase (LOX) gene family, which plays an important role in development, senescence, tumor suppression, cell growth, and chemotaxis." (PMID 32621591, 2020). "26, 27 Moreover, a PC in vivo experiment suggested that salidroside suppressed tumor growth, increased cell apoptosis, inhibited the metastasis of BxPC‐3 cells to the lung, and reduced HIF‐1α, LOXL2, MMP2, and MMP9 while enhanced E‐cadherin in tumor tissue." (PMID 31162697, 2020). "In our future research, we need to construct cell lines that differently expressed LOX and LOXL2 to verify our research results from the aspects of in vivo, in vitro and KIRC tumor tissue." (PMID 32970930, 2020). "Tumor grade and individual cancer stages in KIRC were also significantly affected by higher protein expression of LOX and LOXL2 from CPTAC samples." (PMID 32970930, 2020). "At the post-translational level, GATA6 interacts with LOXL2 in promoting angiogenesis and CCA tumor growth." (PMID 33371259, 2020). "Univariate and multivariate analyses showed that tumor differentiation and co-expression of SP1 and LOXL2 were independent factors for disease-free survival." (PMID 30976063, 2019). "We have showed that LOXL2 was overexpression in HCC and was positively correlated with tumour grade, metastasis, VM formation and poor survival in 201 HCC patients." (PMID 30506621, 2019). "In summary, our study demonstrates that SP1 modulates EMT and is involved in tumor invasion and migration of PDAC cells through the regulation of LOXL2." (PMID 30976063, 2019). "According to the univariate analysis of DFS, the tumor location (head), tumor size (≥20 mm), mesenchymal EMT status, and high LOXL2 expression were significant prognostic factors for PC." (PMID 29959362, 2018). "Reconstitution of N-MSCs with four genes, GREM1, LOXL2, ADAMTS12 and ITGA11 that contributed to the T-MSC phenotype increased their ability to promote primary tumor cell dissemination." (PMID 29503225, 2018). "The multivariate analysis using the Cox proportional hazard model indicated that tumor size (≥20 mm), mesenchymal EMT status and high LOXL2 expression were independent predictive factors for DFS in patients with PC." (PMID 29959362, 2018). "Accordingly, the secreted LOXL2 form HCC facilitates the formation of pre-metastatic niche and the accomplishment of tumor distant metastasis." (PMID 29728125, 2018). "Immunohistochemical staining for the endothelial marker endomucin revealed a significant decrease in tumor angiogenesis and vessel count in both the dual LOX/LOXL2 inhibitor treated mice (PXS-S1A) and the LOXL2 specific inhibitor treated mice (PXS-S2B)." (PMID 28199967, 2017). "LOXL2-activated XBP1 directly promotes upregulation of EMT-TFs that in turn would favour the high aggressiveness and metastasis of those tumour types." (PMID 28332555, 2017).
tumor (continued). "LOXL2 can contribute to tumour expression by inducing an epithelial-to-mesenchymal transition (EMT) in cells, an event that is vital for tumours to become metastatic." (PMID 28845385, 2017). "Lysyl oxidase family members, in particular lysyl oxidase-like 2 (LOXL2), are known to regulate the process of EMT and thus promote tumor progression." (PMID 28449718, 2017). "Here we demonstrate that dormant MCF-7 cells expressing LOXL2 acquire a cancer stem cell (CSC)-like phenotype, mediating their outgrowth in the 3D BME system that models tumor dormancy and outgrowth." (PMID 27655685, 2016). "Tumor spheroids from control transfected and LOX/LOXL2 overexpressing 4T1 cells were generated and cultivated at 20% oxygen levels to keep interferences by endogenous lysyl oxidases at a minimum." (PMID 26620400, 2015). "The RAS pathway target genes LOXL2, SPARC and CTSB exert functions in the remodelling of the extracellular matrix, thereby favouring invasion and metastasis of tumour cells." (PMID 24875049, 2014). "Of remarkably interest is the implication of LOXL2 in the regulation of epithelial-to-mesenchymal transition (EMT) and tumor progression." (PMID 24414204, 2014). "A few pathways and molecules have been so far implicated in the regulation of epithelial plasticity in basal-like tumours, including the Wnt signaling, Forkhead 1 factor FOXC2, and lysyl oxidase-like 2 (LOXL2)." (PMID 23555842, 2013). "Furthermore, LOXL2 has been shown to regulate ERK, p38, and JNK signaling and influence tumor cell proliferation in various cancers, including pancreatic and breast cancers." (PMID 41399365, 2026). "Remarkably, LOXL2 overexpression in PARP9 knockdown cells significantly attenuated apoptosis and enhanced resistance to DNA damage, partially reversing the tumor-suppressive effects of PARP9 knockdown." (PMID 41357999, 2025). "Interaction of PEAR1 with LOXL2 appeared likely to be involved in the effects of PEAR1, since LOXL2 has previously been shown to promote tumor cell proliferation and metastasis and to inhibit tumor cell dormancy, effects which would be blocked by PEAR1-mediated sequestration of LOXL2." (PMID 41185039, 2025). "In addition, RT-qPCR analysis revealed that LOXL2 and SPTBN1 were predominantly expressed in normal cell lines, whereas higher levels of NCKAP1L, RUNX2, and WFS1 were detected in tumor cell lines." (PMID 41164190, 2025). "Compared to the MMA-induced group (MMA.Vector-LOXL2.HPSCs+MIA PaCa-2 group), the LOXL2-KD/MMA group (MMA.sh3-LOXL2.HPSCs+MIA PaCa-2) showed significantly lower LOXL2 expression in tumor tissues, with no significant increase in COL I and αSMA expression." (PMID 40425551, 2025). "We also find that increased linear ECM alignment in both the adjacent normal pancreas and tumor tissues, elevated serum MMA levels, and increased LOXL2+ PSC accumulation in the adjacent normal pancreas are all closely associated with the establishment of an immunosuppressive microenvironment." (PMID 40425551, 2025). "Tumour samples were submitted to immunohistochemistry to detect LOX and LOXL2." (PMID 41408914, 2025). "Inhibiting LOXL2 can reduce ECM stiffness and disrupt the pro-tumor effects of CAFs." (PMID 40909292, 2025). "This suggests that LOXL2 may regulate the expression of IFIT3, which has important implications for tumor progression." (PMID 40061935, 2025). "Furthermore, several studies have shown that LOXL2 can trigger epithelial-mesenchymal transition (EMT) and can act as a tumor suppressor or promoter of metastasis." (PMID 38672570, 2024). "In addition, lab work will identify biomarkers specific for a broader spectrum of cells like LOX, LOXL2, and MAPK15 to reveal cells with invasive phenotypes in the primary tumor and circulation." (PMID 39329988, 2024). "Hypoxic conditions generated in the tumor microenvironment are favorable to LOXL2 overexpression, as the activated HIF-1 binds to the hypoxia-responsive element (HRE) in the promoter region of the LOXL2 gene." (PMID 38672570, 2024).
tumor (continued). "Additionally, CD34, FN1, LOXL2, and VCAN are key players in tumor angiogenesis, invasion, and metastasis." (PMID 39012409, 2024). "CAFs typically secrete CXCL12, TGF-β, LOXL2, HGF, and IL-22 to promote tumor progression." (PMID 36992704, 2023). "Moreover, aminomethylenethiophenes (AMTs) is a potent oral bioavailable anti-tumor agent targeting dual LOX and LOXL2 and exhibit improved pharmacokinetic properties and excellent antitumor efficacy in vivo." (PMID 36906534, 2023). "In summary, the LCN2/LOXL2/MMP9 ternary complex promoted the migration and invasion of cancer cells and malignant tumour progression through multiple mechanisms and could be a potential therapeutic target." (PMID 37753805, 2023). "Given our above results showing that DHA regulates LOXL2/VEGFA expression and affects the fatty acid oxidation program, we presume that DHA may exert a synergistic anti-tumor effect with antiangiogenic drugs." (PMID 37056396, 2023). "Tumor growth and PNI were assessed with inducible ablation of LOXL2." (PMID 37746297, 2023). "In addition to their individual diverse functions, LCN2, MMP9 and LOXL2 are all secreted proteins and are involved in reshaping the ECM, contributing to the progression, invasion, and migration of tumours." (PMID 37753805, 2023). "Considering that growth of tumour cells in vivo occurs in a three‐dimensional environment, 3D cell culture showed that the LCN2/LOXL2/MMP9 ternary complex degraded the extracellular matrix by promoting the formation and extension of filopodia, thereby enhancing the invasion of tumour cells." (PMID 37753805, 2023). "Furthermore, the overexpression of LOXL2 in mouse models increases EMT and stemness, thereby promoting primary and metastatic tumor growth and reducing the overall survival." (PMID 36010993, 2022). "LOXL2 is a protease that modifies the ECM by promoting cross-linking of collagen fibers, is believed to play an important role in tumor progression and fibrosis, with the potential to inhibit tumor progression and reverse fibrosis." (PMID 35770089, 2022). "Without the induction of hypoxia, the expression of LOXL2 is correspondingly reduced, which also facilitates the formation of cell clusters and enhances the migration of tumor cells." (PMID 36293126, 2022). "In fact, this is not contradictory to the previous tumor-promoting effect of LOXL2, because tumor cells in different regions are in diverse environments and have distinct biological behaviors." (PMID 36293126, 2022). "Here we found that LOXL2 and its non-secreted catalytically inactive L2Δ13 splice isoform are able to regulate metabolic reprogramming so as to promote tumor initiation and progression in vitro and in vivo." (PMID 36209516, 2022). "Taken together, inhibition of LOXL2 may be a promising strategy in CAF-targeting management, in terms of inhibiting tumor progression and restoring therapeutic efficacy." (PMID 36555612, 2022). "Moreover, the results showed that the expression levels of LOXL2, PLOD2, MMP14 and SPOCK1 was higher whereas that of DCN was lower in tumor tissues compared with normal tissues." (PMID 36186418, 2022). "In addition to PXS–S1C, several small molecule inhibitors were synthesized and shown both to inactivate LOXL2 (IC50 = 0.008–0.203 μM) and to repress the epithelial–to–mesenchymal transition (EMT), proliferation of tumor cells and progression of fibrosis." (PMID 36362176, 2022). "First, we investigated the correlation between the expression levels of LOXL2 and that of key EMT markers for tumor samples, using various TCGA datasets (BRCA, COAD, COADREAD, OV), and for cancer cell lines using the Cancer Cell Line Encyclopedia (CCLE) dataset." (PMID 33807227, 2021). "IHC analysis of LOXL2 in a tissue microarray revealed that high LOXL2 expression was observed in the majority of PDAC tissues but not in the non-tumor tissues." (PMID 34836938, 2021).
tumor (continued). "LOXL2-regulated ECM-modification plays important roles in induction of EMT 19, vasculogenic mimicry 50, cell adhesion, senescence, and invasion in the local tumor microenvironment." (PMID 34646366, 2021). "In 1997, the LOXL2 gene was recognized as a reduced transcript in kinds of non-adherent tumor cell lines compared to adherent tumor cell lines." (PMID 34970534, 2021). "Here, we demonstrated that LOXL2 could enhance aerobic glycolysis in PDAC cells, thus linking LOXL2 to tumor cell metabolic reprogramming." (PMID 34836938, 2021). "In particular, IL6 and BST2 were significantly induced in all naïve MSCs after 3 days’ coculture with primary tumor cells, whereas the expressions of ADAMTS12, MX2, LOXL2 and GREM1 varied and displayed transient induction during the course of the coculture assay." (PMID 34513701, 2021). "In addition, the forkhead box M1b (FoxM1b), a transcription factor which exerts a pro-tumor effect on HCC, has been reported to play a positive role in LOX and LOXL2 expression." (PMID 33371259, 2020). "Importantly, Loxl2 inhibition using either the pan-Lox inhibitor BAPN or a specific inducible shRNA reduces OS cell proliferation in vitro and decreases tumor growth and lung colonization in murine and human orthotopic OS transplantation models." (PMID 32686768, 2020). "However, LOX and lysyl oxidase-like 2 (LOXL2) inhibition seem to be promising in cancer therapy, as reducing their activity decreased mechanotransduction in vitro and reduced tumor growth." (PMID 32466585, 2020). "While LOXL2 has been involved in the angiogenic response of both normal and tumoral endothelial cells, evidence regarding the contribution of LOX to neovascularization is weak and the studies were mainly focused on tumor angiogenesis." (PMID 31615160, 2019). "In recent clinical trials, simtuzumab, a monoclonal antibody against LOXL2, failed to produce improved anti-tumor benefits when given in combination with other anti-cancer drugs, including 5-fluorouracil, leucovorin, irinotecan (FOLFIRI) and gemcitabine." (PMID 31106200, 2019). "However, multivariate analyses indicated that tumor differentiation and high expression of both SP1 and LOXL2 were independent poor prognostic factors for DFS." (PMID 30976063, 2019). "In vitro mechanistic studies with conditioned tumor cell medium treatment of normal human oral fibroblasts were carried out in the presence and absence of the LOXL2 inhibitor to identify signaling mechanisms promoted by LOXL2 activity." (PMID 31086173, 2019). "In vitro studies identified PDGFRβ as a direct substrate for LOXL2, and indicated that LOXL2 and PDGF-AB together secreted by tumor cells optimally activated PDGFRβ in fibroblasts to promote proliferation and the tendency toward fibrosis via ERK activation, but not AKT." (PMID 31086173, 2019). "In addition, the results that the LOXL2 protein and mRNA levels were negatively correlated with LLGL2 expression in HCC tumour tissues and HCC cell lines were detected in this study." (PMID 30506621, 2019). "Optimal fibroblast proliferation in vitro required LOXL2 activity, while tumor cell proliferation did not." (PMID 31086173, 2019). "In summary, we have shown that Loxl2 expression is not essential for dermal development, homeostasis or tumour stroma formation." (PMID 29953488, 2018). "On the other hand, the univariate analysis of OS revealed that an older age (≥65 years), gender (male), tumor location (head), tumor size (≥20 mm), portal vein invasion, perineural invasion, UICC stage, mesenchymal EMT status, and high LOXL2 expression were significant prognostic factors for PC." (PMID 29959362, 2018). "Weidenfeld and his colleagues recently demonstrated that conditional hypoxic environment triggered endogenous LOXL2 expression in MCF-7 cells and induced EMT and the acquisition of stemness features which eventually activated the transition of dormant tumor cells to metastatic growth." (PMID 30456206, 2018).